APOE (apolipoprotein E)
Diseases named in the same sentence as APOE in open-access papers (continued):
Sharing a sentence is not in itself a finding about the gene and the disease.
Hypertension (continued). "Furthermore, studies using an animal model constructed by multiple mating of TCTP-TG with apolipoprotein E knockout mice (ApoE KO) indicated that TCTP-induced hypertension facilitates the severity of atherosclerotic lesions in vivo." (PMID 36359240, 2022). "Possible clinical implications could be that clinicians should be more aware of hypertension in these APOE ε4 carriers." (PMID 35624902, 2022). "Associations between low-grade inflammation and cognitive performance were analyzed with multivariable linear models adjusted for age, sex, education, APOE ε4 genotype, type 2 diabetes, hypertension, hypercholesterolemia, body mass index, depressive symptoms, smoking, and baseline cognition." (PMID 36195448, 2022). "Measures of closeness revealed that several nodes for females were close to other nodes in the network, but functional connectivity in the DMN, hypertension, waist circumference and ApoE were all above the mean and mI was more than 1 SD above the mean closeness for the other variables." (PMID 34267647, 2021). "Moreover, the complications of abnormal lipid levels (e.g., atherosclerosis, hypertension and/or diabetes, cardiovascular disease, CVD) were also observed to be associated with the APOE ε4 allele in the Asian population." (PMID 34828374, 2021). "However, the apoE-/- mice presented signs of diastolic dysfunction by hypertrophic changes in left ventricle, due probably to arterial hypertension." (PMID 34816004, 2021). "Conversely, the APOE-ε2 allele appears to decrease the risk of heart attack and angina, but not in stroke or high blood pressure." (PMID 34301914, 2021). "However, risk factors including heavy smoking, APOE ε4/ε4 status and WHR had associations of similar magnitude, or greater, than hypertension." (PMID 32971464, 2020). "With 8,300 participants who have completed up to four cognitive assessments, we evaluated the combined effects of the APOE e4 genotype and history of physician-diagnosed hypertension on long-term cognitive function in a large longitudinal cohort of female nurses." (PMID 31697783, 2019). "The PS analysis supports this conjecture, demonstrating that hypertension, the most important known risk factor for ICH, may simply obscure the APOE risks that may be common across ancestries." (PMID 30726504, 2019). "Older age and ApoE allele are not-modifiable risk factors but hypertension can be improved with changing life style." (PMID 31993381, 2019). "Moreover, miR-92b-3p, miR-939-5p, and miR-769-3p were annotated with lipodystrophy, glucocorticoid and apolipoprotein E, which are hypertension-related indicators." (PMID 30975221, 2019). "We, therefore, hypothesize our findings to reflect more broadly the biological interaction between the damaging effects of hypertension and the pathological substrate represented by APOE ɛ4 across a multitude of mechanistic pathways." (PMID 32954261, 2019). "Furthermore, APOE, NOS3, ACE, AGT, and CYP variants influence the therapeutic response to hypotensive drugs in AD patients with hypertension." (PMID 29301387, 2018). "For example, in a study of the epigenetic clock and mortality using data from four cohorts, no consistent associations were found between it and measures such as education, type 2 diabetes, hypertension, apolipoprotein E (APOE) status, smoking or cardiovascular disease." (PMID 27075770, 2018). "Factors such as vascular health (e.g., hypertension), genetics (e.g., apolipoprotein E genotype), cognitive reserve, exercise and social interaction can all affect brain aging, both positively and negatively, which can in turn affect functional activation and behavioral performance outcomes." (PMID 27610082, 2016). "Based on these immune responses to p210 vaccine and the reported participation of CD8+ T cells in hypertension and kidney dysfunction, we hypothesized that p210 vaccine would modulate the hypertensive response in AngII-infused apoE (-/-) mice." (PMID 26121471, 2015).
Hypertension (continued). "There was no confounding by coronary artery disease, type 2 diabetes, hypertension, depressive symptoms, or APOE ε4 allele when each variable was separately included in a model with age and sex (data not shown)." (PMID 26441635, 2015). "Results of multivariable Cox regression demonstrated non-significance (p = 0.17) for peak versus base subjects in a model adjusted for gender, age, BMI, hypertension, metabolic syndrome, smoking, and levels of apoA-I, apoA-II, apoB, apoE, total cholesterol, CRP, HDL-C, and triglycerides." (PMID 22723940, 2012). "On the contrary, others reported both hypertension and myocardial hypertrophy in aged apoE-/- mice." (PMID 22330242, 2012). "Compared with controls, LOAD cases were older (79.8 vs. 73.1 years old), included more females (64% vs. 52%), had a lower education level (≤ 6 years: 50% vs. 11%), and included fewer with hypertension history (38% vs. 54%) or hyperlipidemia (18% vs. 30%), and more ApoE e4 carriers (39% vs. 15%)." (PMID 22272811, 2012). "Prevalent CVD or AF was associated with higher odds for one CSVD marker in those who do not have hypertension compared to those who have hypertension, those not on treatment for hypertension compared to those receiving treatment, and in those who do not have APOE ε4 allele." (PMID 40867146, 2025). "However, the association persisted only for MCI (OR: 0.494, 95% CI: 0.287–0.849, p < 0.05) and not for ad after adjusting for additional variables like hypertension, nutritional risk and APOE genotype." (PMID 40717521, 2025). "Additionally, lower childhood social class, former smoking (compared with never smoking), APOE e4, history of hypertension, and poorer emotional health were associated with lower survival, but these associations were smaller and not robust to FDR correction." (PMID 38941261, 2024). "Multivariable analyses including significant predictors from univariate analyses showed that only the presence of cSS (HR, 7.38; CI 1.42–38.44) and previous lobar ICH (HR, 5.07; CI 1.23–20.87) were associated with ICH development but not hypertension, smoking, and APOE genotypes." (PMID 36635759, 2023). "Therefore, we hypothesized that the renal lesions exhibited by ApoE/NOS3−/− mice were possibly due to a combination of hypertension and reduced salt sensitivity." (PMID 36360235, 2022). "This may be partially explained by epidemiological studies which show that the majority of risk factors for both types of dementia are related to cerebrovascular disease and include APOE-ε4 genotype, advanced age, hypertension, hyperlipidemia, diabetes, obesity, and smoking." (PMID 33329053, 2020). "Finally, carriage of the apolipoprotein-E (APOE) ε4 allele is associated with higher total volume and higher accumulation of WMHs over time, but also shows close interdependence with other CVR factors, such as hypertension." (PMID 32971464, 2020). "In addition to APOE variants and rs646776, ABI3 variant rs28394864 was also associated with cardiovascular traits, such as hypertension (p = 1.60 x 10−13), ischemic heart disease (p = 4.58 x 10−9), coronary atherosclerosis (p = 6.47 x 10−10), and angina (p = 6.51 x 10−9)." (PMID 33152005, 2020). "Interestingly, chronic hypertension has been reported to be associated with tau pathology among APOE e4 carriers, suggesting a plausibility in mechanism through which hypertension may interact with APOE e4 to influence cognitive function." (PMID 31697783, 2019). "However, this lack of information content is likely to bias our score results toward the null; we expect that a more precise index of hypertension burden would have increased our ability to normalize this phenotype across race/ethnicity and to demonstrate even more homogeneous APOE ε4 risks." (PMID 30726504, 2019).
Hypertension (continued). "APOE ε4 appears to be confirmed as a risk factor for lobar intracerebral hemorrhage in nonwhite populations but is masked by differential hypertension burden in Hispanic individuals; further studies are needed to explore the interactions between APOE alleles and environmental exposures." (PMID 30726504, 2019). "For example, data on high blood pressure, APOE e4 gene, depression, medication use, substance misuse, and pre-existing neurological disorders such as Parkinson’s disease and epilepsy were not available in all studies and could not be included as covariates in the analyses." (PMID 30995986, 2019). "Finally, we evaluated whether treatment with BM-573 could prevent the progression of hypertension observed in ApoE-KO mice." (PMID 27019366, 2016). "In all patients, after adjusting for age, sex, hypertension, and time to CT, the presence of the APOE ε4 allele (OR 2.020, 95% CI 1.064–3.834, p = 0.032) was associated with the island sign, whereas the presence of the APOE ε2 allele (OR 0.734, 95% CI 0.339–1.593, p = 0.435) was not." (PMID 40051977, 2025). "Binary logistic regression analysis revealed that neither continuous FSH nor dichotomized FSH was associated with the risk of AD-D after adjusting for age, years of education, history of hypertension and depression, WC, FT3, E2, TT, and APOE ε4 genotype." (PMID 41180813, 2025). "In NDPD, the development of CI during the 5-year follow-up can be predicted with good accuracy using a model combining age, current diagnosis of hypertension, baseline MoCA scores, MDS-UPDRS III scores, and APOE status." (PMID 36926634, 2023). "Further studies should establish the effect of mTBI on the ApoE-cyclophilin-NF-kB-MMP-9 pathway and BBB function in aging and hypertension." (PMID 38073626, 2023). "ApoE/NOS3−/− mice can reach a blood pressure of 133.00 ± 3.85 mmHg in adulthood and suffer from hypertension." (PMID 36360235, 2022). "However, critically, in individuals with clinically significant hypertension, only those with lower cerebral blood flow demonstrated the negative association between APOE-ε4 and executive function on the Trail Making Test (part B), compared to individuals with higher cerebral blood flow." (PMID 36324708, 2021). "As results, the identified findings using network pharmacology analysis had identified total six hug genes of metformin treating obesity/hypertension, including IL6, CCL2, LEP, APOB, SERPINE1, and APOE." (PMID 34334083, 2021). "These factors included hemispheric location, sex, aging, smoking status, APOE carrier status, history of T2DM, hypertension, hyperlipidemia, and some important MRI features (CMBs, WMHs, and cerebral microinfarcts) in elderly people in the community." (PMID 33935681, 2021). "We analyzed the relationships among hypertension, CMB, and ICH, as well as the roles of other vascular factors including ApoE genotype." (PMID 28555127, 2017). "In addition, APOE ε4 might also contribute to lead-related hypertension." (PMID 27584680, 2016). "In our study, infusion of apoE (-/-) mice with AngII significantly changed the cytokine profile of CD8+ T cells, supporting the role of this T cell subtype in hypertension." (PMID 26121471, 2015). "For instance, the joint effect of APOE ε4 (≥1 copy) and hypertension (yes vs. no) resulted in a HR of 2.26 (95% CI: 1.95–2.63) in women compared the women without these exposures." (PMID 41536502, 2026). "Specifically, the effect of WMH on ΔMemory was not affected by demographic information, APOE ε4 status, baseline cognitive status, or previous disease status including hypertension and smoking (p < 0.001 and 0.010 for model 1 and model 2, respectively)." (PMID 39328245, 2024).
Hypertension (continued). "At baseline, NDPD patients with CI were older and they had a higher proportion of male sex, current diagnosis of hypertension, Hoehn and Yahr stage 2, and APOE ε4 homozygotes than those without CI during the 5-year follow-up." (PMID 36926634, 2023). "Predictive accuracy of CI using age alone improved by the addition of clinical variables and biomarkers (current diagnosis of hypertension, baseline MoCA scores, and MDS-UPDRS III scores, APOE status; AUC 0.80 [95% CI 0.74–0.86] vs. 0.71 [0.64–0.77], p = 0.008)." (PMID 36926634, 2023). "Apolipoprotein E (ApoE) knockout mice with BMP4 knockout in adipose tissue or brown adipose tissue (aP2-DKO or UCP1-DKO, respectively) were used for exploring the role of impaired PVAT metabolism in hypertension." (PMID 36457800, 2022). "The APOE rs429358 and MTHFR rs1801133 genotypes in co-dominant, dominant, and recessive models were not significant risk factors for hypertension." (PMID 36158751, 2022). "Interestingly, research among people with arterial hypertension showed a significant rise in apo-CIII and apoE supporting our results." (PMID 35205153, 2022). "Unlike ApoE, the betweenness of hypertension appears to be driven more by its relationship with other MetS risk factors rather than a position between brain integrity and MetS." (PMID 34267647, 2021). "Using this algorithm, all hug targets of metformin against obesity-related hypertension were identified accordingly, including IL6, CCL2, Leptin (LEP), Apolipoprotein B (APOB), serine protease inhibitor clade E member 1 (SERPINE1), Apolipoprotein E (APOE)." (PMID 34334083, 2021). "Multivariable-adjusted* mean differences (95% CI) in average cognitive performance in up to 4 assessments (1995–2008), by APOE e4 status an history of physician-diagnosed hypertension (n = 8300; 1995–2008), with and without treatment." (PMID 31697783, 2019). "Significant interaction was detected between the APOE e4 allele and untreated hypertension (p-int = 0.02 for the TICS; p-int = 0.045 for global score), but not with treated hypertension." (PMID 31697783, 2019). "Sex was coded 0 for female and 1 for male, APOE 4 positivity was coded 0 for APOE4 non-carriers and 1 for APOE4 carriers, and a history of hypertension was coded 0 for the absence of hypertension history and 1 for the presence of hypertension history." (PMID 30337868, 2018). "We chose this dose as Ang II at 0.8 mg kg−1 per day was not sufficient to induce aortic aneurysms in irradiated ApoE−/− mice in comparison with non-irradiated mice receiving this dose, despite being sufficient to induce hypertension." (PMID 25782711, 2015). "MCI patients who were APOE ε4 noncarriers more often had hypertension and had lower ADAS-Cog/MCI scores than MCI patients who were APOE ε4 carriers." (PMID 25478019, 2014). "Included and excluded subjects compare favorably on distribution of sex, family history, APOE-4, history of hypertension at baseline, and time between assessments (data not shown)." (PMID 22536535, 2012). "In the multivariable analysis, after adjusting for prespecified predictors, including age, sex, hypertension and time to CT, the presence of neither APOE ε4 (OR 0.673, 95% CI 0.193–2.351, p = 0.535) nor APOE ε2 (OR 0.577, 95% CI 0.166–2.002, p = 0.386) was associated with the island sign." (PMID 40051977, 2025). "Conditional logistic regression analysis revealed that BMI, hypertension, traditional lipid parameters (TC and LDL-C), and non-traditional lipid parameters (nonHDL-C, APOB, APOE, ATH index, AI, CRI-I, CRI-II, and LCI) were risk factors for the onset of SSNHL (Model 1)." (PMID 38714080, 2024). "In the regression analysis of APOE and CCA-IMT at baseline, we found that E2 carriers had lower mean CCA-IMT (β: − 0.02 [95% CI − 0.04, − 0.004]) than E3 homozygotes when adjusting for age, sex, BMI, smoking status, alcohol consumption, sedentary lifestyle, hypertension and type 2 diabetes." (PMID 35332187, 2022).
Hypertension (continued). "Women residing in the Midwest and who had higher education or income, were currently employed, currently drinking alcohol, did not have hypertension, and did not carry the ApoE e4 genotype had higher mean cognitive scores on both TICSm and CVLT at baseline, compared to their counterparts." (PMID 35113870, 2022). "However, women with treated hypertension had average cognitive scores that were comparable to women without a history of hypertension among carriers of the APOE e4 genotype." (PMID 31697783, 2019). "CETP TaqI B and APOE HhaI polymorphism may not be associated with type II diabetes mellitus in North Indian population, however CETP TaqI B polymorphism may be associated with hypertension along with T2DM." (PMID 15992403, 2005). "Potential differences in patient characteristics, such as gender (p = 0.04), and clinical factors like hypertension and ADAS-Cog scores, were significantly different between APOE carriers and non-carriers." (PMID 39939901, 2025). "Patients in the lobar ICH group were older and had less hypertension, but had a greater ICH volume and a higher percentage of previously ICH, island sign and APOE ε4 carriers, compared to those in the nonlobar ICH group." (PMID 40051977, 2025). "The SSNHL group exhibited significantly higher prevalence rate of hypertension and higher levels of body mass index (BMI), TC, LDL-C, nonHDL-C, APOB, APOE, ATH index, AI, CRI-I, CRI-II, and LCI compared to the control group, with statistical significance." (PMID 38714080, 2024).